LZTR1 (leucine zipper like post translational regulator 1)
Diseases named in the same sentence as LZTR1 in open-access papers (continued):
Sharing a sentence is not in itself a finding about the gene and the disease.
Noonan syndrome (continued). "To date, more than 15 genes associated with Noonan syndrome have been reported, among which, variants of LZTR1 have been newly associated with the etiology of Noonan syndrome since 2014." (PMID 33407364, 2021). "Germline mutations of leucine zipper-like transcriptional regulator 1 (LZTR1) are associated with Noonan syndrome and familial schwannomatosis." (PMID 32344852, 2020). "Noonan syndrome, first described in 1963 by Jacqueline Noonan, is a relatively common multisystem disorder predominantly inherited in an autosomal-dominant pattern, though autosomal-recessive inheritance linked to LZTR1 mutations has also been reported." (PMID 39860591, 2025). "Noonan syndrome is generally considered an autosomal dominant condition, but recent studies suggest that the LZTR1 gene may be implicated in both dominant and recessive forms of the disorder." (PMID 41229399, 2025). "Lztr1 autosomal dominant mutation induces Noonan syndrome-like phenotypes in mice." (PMID 40724954, 2025). "LZTR1 is associated with Noonan syndrome which includes HCM as part of the disease." (PMID 39472908, 2024). "Patients with pathogenic missense mutations in LZTR1 exhibited a characteristic Noonan syndrome." (PMID 37627046, 2023). "Mutations in LZTR1 are associated with cancers and Noonan syndrome, the most common RASopathy." (PMID 34222248, 2021). "Moreover, two compound heterozygous missense mutations in the LZTR1 gene were identified in one patient with the Noonan syndrome phenotype and HCM." (PMID 30732632, 2019). "It efficiently edits the aberrant donor splice site in the LZTR1 gene, resulting in the restoration of LZTR1 expression in cardiomyocytes derived from patients with Noonan syndrome." (PMID 40027883, 2025). "Mechanistically, LZTR1 deficiency results in accumulation of RAS GTPases and, as a consequence, in RAS-MAPK signaling hyperactivity, thereby causing the Noonan syndrome-associated phenotype." (PMID 38333672, 2024). "Autosomal dominant mutations in LZTR1 causes dysregulation of RAS proteostasis and induces Noonan syndrome-like phenotypes in a novel mouse model." (PMID 39352760, 2024). "Mutations associated with Noonan syndrome alone include CBL, BRAF, KRAS, LZTR1, MAP2K1 (MEK1), NRAS, PTPN11, RAF1, RIT1, SOS1 and SOS2." (PMID 38550930, 2023). "WES revealed a leucine-zipper-like transcription regulator 1 (LZTR1) variant, indicating Noonan syndrome (NS)." (PMID 37143668, 2023). "The KRAS gene, along with LZTR1 and SOS2, is one of the three Noonan syndrome-causing genes in this group." (PMID 35813072, 2022). "Variants in FZD2 and LZTR1 were described in individuals with Robinow syndrome-like phenotype (FZD2) and Noonan syndrome (LZTR1), respectively." (PMID 30809043, 2019). "We herein describe a family with LZTR1-related Noonan syndrome." (PMID 33407364, 2021). "So far, less than 50 cases of Noonan syndrome have been associated with LZTR1 variants, making its genetic pattern not well understood." (PMID 33407364, 2021). "Meanwhile, prolonged activation of PI3K/AKT and ERK signaling disrupts the regulation of cell growth and division, leading to the characteristic features of Noonan syndrome (OMIM# 163950) that is caused by germline variation in KRAS genes (PTPN11, SOS1, RAF1, LZTR1, etc.)." (PMID 31752936, 2019).
Noonan syndrome (continued). "Over the years, several other genes involved in Noonan syndrome (KRAS, SOS1, RAF1, MAP2K1, BRAF, NRAS, RIT1, and LZTR1) have been identified, acting at different levels of the RAS-mitogen-activated protein kinase pathway." (PMID 38254922, 2023). "Additionally, eight were syndromic patients: four with Noonan syndrome (PTPN11 and biallelic LZTR1), two with Danon disease (LAMP2), two with Carvajal syndrome (DSP), and one with atypical glycogen storage disease (PRKAG2)." (PMID 40642871, 2025). "However, the pathogenesis and inheritance pattern of LZTR1 in Noonan syndrome have not yet been elucidated." (PMID 33407364, 2021).
schwannoma (23 papers, 2015 to 2026). A benign, usually encapsulated slow growing tumor composed of Schwann cells. "Additional scRNA-seq analyses of schwannomas from patients with characterized germline variants in either SMARCB1 or LZTR1 would be instructive in order to elaborate any transcriptome differences that remain to be identified." (PMID 40794298, 2025). "The LZTR1 variant in patient 55 has been previously reported to associate with rare cancers affecting the nervous system such as schwannomas." (PMID 40627234, 2025). "Mutations in SMARCB1 or LZTR1 disrupt their normal functions, leading to the formation of multiple schwannomas." (PMID 40764996, 2025). "This is supported by evidence from people with 22q11.2 deletion syndrome who have large germline deletions that normally include the LZTR1 gene and appear to have a lower risk of schwannomas than the general population." (PMID 41284083, 2025). "Studies have shown evidence for additional somatic mutations in NF2 in schwannomas characterized by germline mutations in LZTR1 or SMARCB1, further supporting evidence for the four-hit/three-step model of schwannomagenesis." (PMID 39796693, 2024). "The new classification of schwannomatoses is based on the coupling of the causative genes (i.e., NF2, SMARCB1 and LZTR1) and on the histological hallmark of these syndromes (i.e., schwannomas)." (PMID 35741273, 2022). "It is, therefore, possible that a genetic factor in close linkage with LZTR1 is required to activate schwannoma formation when an LZTR1 LoF variant is present." (PMID 35391499, 2022). "Despite the identification of causative genes, including NF2 (Merlin), INI1/SMARCB1, and LZTR1, the exact molecular mechanism of schwannoma development is still poorly understood." (PMID 32960816, 2020). "Lastly, although the functions of INI1/SMARCB1 and LZTR1 in schwannomagenesis are still unclear, recent research shows that subsequent biallelic loss of Nf2 is necessary to induce schwannoma formation." (PMID 32960816, 2020). "Two patients have been identified with clinically symptomatic schwannomas restricted to one limb, suggestive of somatic mosaicism; however, germline LZTR1 mutations were identified in these patients." (PMID 27921248, 2017). "The 3-step model of tumorigenesis appears to apply to the majority of LZTR1 mutation-positive schwannomas." (PMID 27921248, 2017). "In most schwannomas from patients harbouring LZTR1 germline mutations, the chromosome 22 is retained that harbours the germline LZTR1 mutation and an NF2 allele with a somatically acquired tumour-specific mutation." (PMID 27921248, 2017). "Patients with unilateral vestibular schwannoma and other schwannomas may have an LZTR1 heterozygote pathogenic variant." (PMID 41160189, 2025). "However, the high frequency of LoF LZTR1 variants in the general population suggests that LZTR1 variants confer a reduced risk of schwannomas compared to germline NF2 and SMARCB1 pathogenic variants, making classification of novel variants challenging." (PMID 35391499, 2022). "A mutation in LZTR1 has been described once in anintracranial schwannoma of unknown VGLL status." (PMID 41522855, 2026). "By contrast, the molecular signature of schwannomas from patients with genetically confirmed LZTR1- or SMARCB1-related SWN has been analysed so far only in a single study." (PMID 40794298, 2025). "Most likely, larger numbers of SWN-schwannomas should be analysed comparatively in order to identify any molecular differences between schwannomas derived from patients with either LZTR1- or SMARCB1-related SWN." (PMID 40794298, 2025). "Approximately 8-Mb away from NF2 and commonly involved in schwannoma tumorigenesis is the LZTR1 gene." (PMID 39796693, 2024). "The four-hit, three-step model, is also present in schwannomas from LZTR1 patients, involving LZTR1 and NF2 genes." (PMID 25739810, 2015). "Schwannomas of LZTR1 positive patients also follow a three-step four hit model involving LZTR1 and NF2 genes." (PMID 25739810, 2015).
schwannoma (continued). "For patients with unilateral VS and other non-intradermal schwannomas, LZTR1 variants must ideally be ruled out before confirming a diagnosis of NF2-SWN." (PMID 41160189, 2025). "Furthermore, upregulation of the RAS/MAPK pathway was observed in schwannomas of patients with LZTR1-related SWN." (PMID 40794298, 2025). "A germline LZTR1 stop gained P/LP carrier with schwannoma (PT_BWFTKJXT) exhibited increased intron 14 retention directly upstream of this variant that was associated with significant transcript loss relative to other schwannomas (R=−0.71, p=9.5e-3), suggesting a mechanism of LZTR1 inactivation." (PMID 39974082, 2025). "Remarkably, 57% of patients clinically diagnosed with non-NF2-related SWN but without germline LZTR1 or SMARCB1 lesions exhibit mosaic NF2-related SWN as determined by identical pathogenic NF2 variants detected in two independent schwannomas." (PMID 40794298, 2025). "We present a case of a 51-year-old male with a pseudoglandular cellular schwannoma arising from the brachial plexus, which contains the expected molecular aberrations for a schwannoma (chromosome 22q loss encompassing the NF2 and LZTR1 genes) as well as a FUS::KLF17 rearrangement." (PMID 40878925, 2025). "The absence of reported schwannoma in the literature and in two large series of patients with 22q11.2DS suggests that the typical large deletion at 22q11.2, including LZTR1, is not a risk factor for schwannoma." (PMID 33879870, 2021). "Schwannomas from patients with nonsense or frameshift LZTR1 mutations do not exhibit LZTR1 protein immunostaining, whereas patients carrying splicing or missense variants showed reduced immunostaining." (PMID 27921248, 2017). "In a total of 153 patients aged younger than 24 years with an isolated schwannoma, genetic testing indicated that 15 (9.8%) patients had a germline NF2 pathogenic variant, six patients (3.9%) had a germline SMARCB1 PV, and 10 patients (6.5%) had a germline LZTR1 PV." (PMID 40794298, 2025). "As a disease, it is classified by at least one schwannoma confirmed pathologically and a common variant of SMARCB1, LZTR1, or loss of heterozygosity at chromosome 22q in two anatomically separate schwannomas and without the presence of bilateral vestibular schwannomas." (PMID 41001135, 2025). "However, not all schwannomas from patients with LZTR1 germline mutations exhibit this pattern of mutational events similar to that observed in some schwannomas of patients with germline SMARCB1 mutations." (PMID 27921248, 2017). "However, no detectable mosaicism was found in six patients without SMARCB1 and LZTR1 mutations in their blood, as determined by analysing multiple schwannomas from these patients." (PMID 27921248, 2017). "The basis of the four-hit/three-step model is that all three tumour suppressor genes known to be relevant to schwannoma development, namely NF2, LZTR1 and SMARCB1, are located on chromosome 22q." (PMID 40794298, 2025). "Instead, tumorigenesis of schwannomas in patients with SMARCB1‐ (and LZTR1-) related SWN appears to follow a four‐hit/three‐step model that includes somatic biallelic inactivation of the NF2 gene." (PMID 40794298, 2025). "We were struck by this result since LZTR1, a member of the Kelch-like (KLHL) family and an adapter for Cullin 3 (CUL3) ubiquitin ligase complexes, is considered a tumor suppressor in schwannoma and glioblastoma." (PMID 35197475, 2022). "Furthermore, LZTR1 as a gene predisposing to hereditary schwannomas was only known since 2014 and hence may not be tested in patients who underwent genetic testing prior to that." (PMID 35698239, 2022). "Consequently, the studies reporting lower LZTR1 mutation detection rates included a more heterogeneous group of patients whose schwannomas may not have been characterized by biallelic NF2 inactivation." (PMID 27921248, 2017).
schwannoma (continued). "MRI is used to identify schwannomas and rule out vestibular schwannomas, while genetic testing focuses on identifying mutations in the SMARCB1 and LZTR1 genes." (PMID 40764996, 2025). "Isolated schwannomas in patients with SMARCB1-, LZTR1- or NF2-related SWN may already be present in early childhood or in young adults." (PMID 40794298, 2025). "The SH3PXD2A-HTRA1 fusion gene was detected in 2/24 (8.3%) of schwannomas from patients with SMARCB1-related SWN, and in 13/64 (20.3%) of schwannomas from patients with LZTR1-related SWN which is not significantly different." (PMID 40794298, 2025). "Nevertheless, it is plausible that the events which drive schwannoma growth differ depending upon the presence or absence of a germline PV in one of the three schwannoma predisposition genes (NF2, SMARCB1 and LZTR1)." (PMID 40794298, 2025). "Furthermore, immunohistochemical staining indicated normal protein expression levels of SMARCB1, LZTR1, and NF2 in both schwannomas." (PMID 27921248, 2017). "The affected family members did not appear to harbour germline mutations in SMARCB1, LZTR1, or NF2; nor were somatic mutations of these genes detected in two schwannomas from two family members." (PMID 27921248, 2017). "However, significant differences in the molecular profiles of schwannomas derived from patients with either LZTR1- or SMARCB1-related SWN were not obvious." (PMID 40794298, 2025). "The molecular mechanism underlying the tumorigenesis of schwannomas in patients with SMARCB1- (and LZTR1-) related SWN is clearly not in agreement with the classic Knudson two‐hit model hypothesis involving the biallelic inactivation of a single tumour suppressor gene." (PMID 40794298, 2025). "Furthermore, schwannomas of patients with SMARCB1- and LZTR1-related SWN are phenotypically and histopathologically indistinguishable from schwannomas of patients with NF2-related SWN and sporadic schwannomas." (PMID 40794298, 2025).
RASopathies (22 papers, 2019 to 2025). "Almost all pathogenic mutations in RASopathies follow AD inheritance patterns, whereas pathogenic mutations in LZTR1 have been identified in both AD and AR hereditary forms." (PMID 39352760, 2024). "Differently from other affected RASopathy genes with the established dominant effect of LP/P variants, LZTR1 has been linked to both dominant and recessive forms of NS." (PMID 38654924, 2024). "The NGS analysis using a panel including genes associated to RASopathies identified the heterozygous variant NM_006767: c.1602del (p.Lys534Asnfs*22) in LZTR1." (PMID 39062695, 2024). "Although recent progress has been made in understanding LZTR1-mediated RAS proteostasis using animal models of RASopathies and leukemogenesis, the influence of LZTR1 deficiency on metastasis is poorly understood." (PMID 37626065, 2023). "Mutations in LZTR1 have been identified in patients with RAS/MAPK signaling pathway-dependent congenital malformation syndrome (RASopathies), glioblastoma, and several cancers via activation of the RAS/MAPK signaling pathway." (PMID 37626065, 2023). "In a subset of RASopathies, the causal mutations are in the LZTR1 protein, a substrate adaptor for E3 ubiquitin ligases that promote the degradation of Ras proteins." (PMID 35114566, 2022). "Given that Lztr1 is a RASopathy gene and implicated in regulating RAS and the MAPK pathway, we analyzed MAPK pathway activation in the brain using p-ERK1/2 expression." (PMID 34222248, 2021). "Molecular confirmation of the NF1 was essential to avoid misdiagnosing NF-NS as other RASopathies with overlapping features, such as café-au-lait spots and lentigines, seen in Legius syndrome, NS, NS with multiple lentigines, and heterozygous LZTR1 variants." (PMID 40289159, 2025). "In addition, variants were identified in a wide range of other RASopathy-associated genes, including LZTR1, BRAF, SOS1, and RAF1, underscoring the necessity of broad genetic testing approaches such as WES in cases with overlapping phenotypes." (PMID 41292581, 2025). "Classifying variants in LZTR1 is more complex than in other RASopathy-associated genes because variants may cause dominant or recessive disease." (PMID 40496714, 2025). "Most RASopathies are associated with an autosomal dominant mode of inheritance, one exception being Noonan syndrome, where recessive phenotypes caused by mutations in LZTR1 and SPRED2 have been described." (PMID 38672195, 2024). "Hence, our data which indicate that Lztr1 loss increases OPC populations is in line with other studies on RASopathy mutations at various levels of the pathway." (PMID 34222248, 2021). "It is still unknown whether these LZTR1 LoF variants could be associated with RASopathies." (PMID 40724954, 2025). "These included a pathogenic variant in TAFAZZIN:c.284+5G>A (Barth syndrome), a variant of unknown significance (VUS) in MYBPC3:c.1224-80G>A and 2 compound heterozygous LP variants in LZTR1 (LZTR1:c.1943-256C>T and LZTR1:c1261-3C>G) in a patient with clinical features of RASopathy." (PMID 38586174, 2024). "Our ability to detect pathogenic variants in genes such as LZTR1, MAPK1, and SOS1 supports the utility of WES in uncovering less common causes of RASopathies." (PMID 41292581, 2025). "One of these is LZTR1, a known RASopathy gene that targets proteins in the RAS pathway for degradation, Similarly, LHX2 (pLI = 0.99), encodes a transcriptional activator; mouse knockouts produce CHD." (PMID 40127276, 2025). "LZTR1 encodes the BTB-kelch superfamily proteins which control various fundamental cellular processes, with a strong association with RASopathy." (PMID 38586174, 2024). "Accumulation of RIT1 through the loss of LZTR1-mediated proteasomal degradation increases MAPK signaling, a defining feature of RASopathies." (PMID 37450595, 2023).
RASopathies (continued). "Three patients in the ESTAND cohort had findings in pleiotropic genes SPRED1, NF1, and LZTR1 linked to developmental syndromes referred to as RASopathies, including various cancerous and non-cancerous tumors as part of the respective syndromic phenotype." (PMID 40060932, 2025). "The biochemical relationship between the RASopathy proteins KRAS, RIT1 and LZTR1 was tested in zebrafish and fruit flies; all LZTR1 orthologs preferentially interacted with RIT1 orthologs, indicating that this interaction is also conserved in less-complex model organisms." (PMID 38672195, 2024).